PPARG (peroxisome proliferator activated receptor gamma)
Diseases named in the same sentence as PPARG in open-access papers (continued):
Sharing a sentence is not in itself a finding about the gene and the disease.
Obesity (continued). "Phosphorylation of PPARγ by CDK5/ERK does not alter its adipogenic activity, but modifies expression of a specific set of genes with impact in obesity and diabetes." (PMID 38735390, 2024). "Marciano et al107 reported a PPARγ antagonist SR1664, which blocks obesity-induced serine 273 phosphorylation in the absence of classical agonists." (PMID 38523674, 2024). "According to the first perspective, we found a reduced transcript level of PPARγ, C/EBPα, and LXRwhile the expression level of SREBP1c, FAS, and ACC was higher in adipose depots of subjects with obesity compared to the non-obese counterparts." (PMID 37106328, 2023). "Our results suggest that, in contrast to rosiglitazone, Peptide 2 does not activate PPARγ and, in conditions of HFD-induced obesity and IR, Peptide 2 does not worsen HFD-induced hepatic steatosis." (PMID 36837793, 2023). "Dietary addition of capsaicin promoted WAT browning to fight obesity but did not prevent obesity in TRPV1−/− mice, suggesting that activation of the TRPV1 pathway promotes the interaction between PPARγ and PRDM16 protein to protect against obesity." (PMID 35462933, 2022). "The effects of CR in the AT on PPARα and PPAR-β/δ have not been shown yet, but it is known that CR and PPARγ agonists can improve the reduced mitochondrial function in the WAT due to aging and obesity." (PMID 30037087, 2018). "Moreover, the ability of SAFA, like palmitate to activate TLR in macrophages is counteracted by PPARγ; mice lacking PPARγ in myeloid cells, upon HFD, develop obesity and IR." (PMID 31683535, 2019). "It specifically inhibited the transactivation activity of PPARγ, but not that of PPARα, β/δ and LXR α,β, by repressing the adipocyte differentiation and ameliorating obesity, insulin resistance, steatosis and hyperlipidemia in diet-induced obesity mice." (PMID 27283034, 2016). "The anti-obesity effect of CS and OB extract in HFD-fed mice might have resulted from suppressing the expression of adipogenic genes, such as PPARγ and FAS, rather than stimulating metabolic oxidation of fatty acids as measured by CPT-1 expression in this study." (PMID 33643424, 2021). "In addition, the high plasma MIF levels did not alter adipogenesis gene PPARγ and FASN expression, suggesting that MIF-mediated AMPK/JNK activation in adipose tissue selectively impacted HSL and lipolysis during the development of adipocyte hypertrophy and obesity." (PMID 37935315, 2024). "Therefore, our findings establish that specific targeting of PPARγ, CB2 and HIF pathway with VCE-004.8 may be a therapeutic approach for the management of obesity and T2D, without the harmful effects on adipogenesis and osteoblastogenesis associated with PPARγ full agonists." (PMID 30382123, 2018).
Insulin resistance (1,035 papers, 2004 to 2026). Increased resistance towards insulin, that is, diminished effectiveness of insulin in reducing blood glucose levels. "PPARγ alterations have been linked to the pathogenesis of MASLD through insulin resistance, inflammation or even oxidative stress." (PMID 41575476, 2026). "PPARG regulates glucose homeostasis and adipocyte differentiation; mutations or alterations in this gene are associated with insulin resistance and T2D development." (PMID 40559391, 2025). "Pathological changes and insulin resistance occur following the loss of PPARγ function or gene mutations, leading to the development of T2DM." (PMID 40386230, 2025). "These pathways are tightly linked to insulin resistance and are recognized as upstream regulators of PPARγ." (PMID 41368574, 2025). "Hydroxyl linoleic acid acts as an agonist of peroxisome proliferator-activated receptor γ (PPARγ), which is implicated in inflammation, atherosclerosis, insulin resistance, and glucose metabolism." (PMID 39590846, 2024). "Clinical trials have also indicated that increased insulin resistance and hepatic PPARγ expressions were associated with NASH scores in some obese patients." (PMID 39436790, 2024). "For example, peroxisome proliferator-activated receptor gamma (PPARG) is a nuclear receptor involved in insulin resistance, lipid metabolism and inflammation, and mutations in the corresponding gene are linked to PLD." (PMID 38231342, 2024). "Attenuation of peroxisome proliferator-activated receptor-gamma reducesglucose transport into adipocytes, impairs fat deposition in the subcutaneousadipose tissue and causes whole-body insulin resistance." (PMID 39076340, 2024). "This PTM further enhances PPARg and NcoR association, ultimately resulting in endothelial insulin resistance." (PMID 38540730, 2024). "We described a case of FPLD3 in a Saudi female presenting with lipoatrophic diabetes, insulin resistance, and hypertriglyceridemia caused by a novel heterozygous pathogenic missense variant of c.1024C>T mutation in the PPARγ gene." (PMID 39596129, 2024). "Phospholipase A/acyltransferase 3 (PLAAT3) inactivation has been linked to insulin resistance and reduced adipocyte differentiation via the PPARγ signaling pathway in human adipose stem cells." (PMID 39684239, 2024). "Loss of PPARγ function has been shown to promote insulin resistance, suggesting a critical role for PPARγ in insulin signalling associated with adipose tissue metabolism." (PMID 38874666, 2024). "Further studies are needed to clarify the precise molecular mechanisms by which the TFG regulates thyroid hormone actions and PPARγ activities, specifically in vivo, and its therapeutic potential for preventing steatosis and the associated insulin resistance." (PMID 38681675, 2024). "Our study reveals a sex-dimorphic functional role for TNFAIP8 in adipocytes potentially through the control of PPARG and estrogen that increases insulin resistance and T2D risk, specifically in women." (PMID 39277575, 2024). "Peroxisome proliferator-activated receptor γ (PPARγ) gene mutations in humans and mice lead to whole-body insulin resistance and partial lipodystrophy." (PMID 36835312, 2023). "The differential genes contained a large number of adipogenic-related genes, among which the heat map lists 60 adipogenic-associated genes involved in the PPARγ signaling pathway, fatty acid metabolism, and insulin resistance." (PMID 36755591, 2023). "The results of an experiment in rodents suggest that the expression pattern of the PPARG gene is associated with high fat intake, adipocyte development, and insulin resistance." (PMID 36982283, 2023). "It has been shown that polymorphisms in the PPARG gene are involved in the development of both insulin resistance and impaired insulin secretion by pancreatic beta-cells." (PMID 36902173, 2023).
Insulin resistance (continued). "The lower expression of PPARγ, as a gene encoding marker of adipose cell differentiation, has also been reported in scWAT of obese individuals with insulin resistance." (PMID 37219669, 2023). "Subjects who had the reference allele in PPARGC1A and the variant allele of PPARγ exhibited higher fasting insulin levels, insulin resistance, and insulin area under the curve compared to those with the other combinations." (PMID 37513946, 2023). "PPARG was expressed in renal glomeruli and tubules and associated with inflammation, oxidative stress, and renal insulin resistance." (PMID 35855831, 2022). "Insulin resistance is the primary cause of type 2 diabetes mellitus and the presence of the G allele in PPARG Pro12Ala improves insulin sensitivity." (PMID 35265101, 2022). "PPARγ inactivation causes severe lipodystrophy and insulin resistance, and precursor cells fail to induce any lipid accumulation when lack of PPARγ, that cannot be even restored by ectopic expression of C/EBPα." (PMID 35921899, 2022). "Even though excessive adiposity and obesity are frequently linked to diabetes and insulin resistance, PPARγ works as an insulin sensitizer by encouraging the development of adipose tissue." (PMID 36552725, 2022). "By activating the nuclear receptor for PPARγ, which is associated with insulin resistance, adiponectin has become a marker of both insulin sensitivity and insulin resistance." (PMID 35628118, 2022). "Our in vitro results confirmed that morusin blocked the overexpression of PPARG caused by insulin resistance." (PMID 36278175, 2022). "Previous research has found that activation of PPARγ can promote the conversion of M1 type macrophages to M2 type macrophages, improve insulin resistance caused by obesity, and reduce the expression of inflammatory factors." (PMID 35757707, 2022). "Other research data supported an association between PPARG Pro12Ala (rs1801282) polymorphism and insulin resistance in Mexican children with dyslipidemia." (PMID 36466447, 2022). "Surprisingly, PPARγ deletion was also demonstrated to cause insulin resistance in skeletal muscle and impair muscle stem cells expansion and myogenesis after injury, indicating PPARγ has tissue-specific effects." (PMID 34881260, 2021). "Computational analysis identified five PPARγ variants expressed in cancer tissues and associated with insulin resistance and partial lipodystrophy, including C162S, R166W, Q286P, Q314P and P467L." (PMID 33467499, 2021). "Upon binding to PPARγ, this coregulatory protein causes differential expression of a set of genes that promotes insulin resistance, which can lead to the development of T2DM." (PMID 34339734, 2021). "Various mutations in PPARγ, causing loss of function, have been shown to strongly associate not only with insulin resistance and diabetes but also with severe hypertension." (PMID 34966295, 2021). "PPARγ activation improves insulin resistance by regulating the expression of adipokines and genes encoding proteins involved in glucose and lipid metabolism." (PMID 34199668, 2021). "In contrast, PPARγ dominant-negative mutations result in hypertension and insulin resistance, suggesting that a relationship exists between PPARγ function and metabolic syndrome." (PMID 34938205, 2021). "PPARγ agonists increase insulin sensitivity and ameliorate salt sensitivity, whereas deficiency of PPARγ results in severe insulin resistance and hypertension." (PMID 34966295, 2021). "Single nucleotide polymorphisms in PPARγ gene are commonly associated with insulin resistance and diabetes." (PMID 34445309, 2021). "On the other hand, it has been reported that high-fat diet (HFD)-induced adipocyte hypertrophy and insulin resistance are improved in heterozygous PPARγ-deficient mice as compared with the wild type mice." (PMID 33494317, 2021).
Insulin resistance (continued). "In contrast, accumulation of anti-inflammatory PPARγ positive macrophages (M2 macrophages) leads to improvements in AT inflammation and insulin sensitivity, while loss of macrophage PPARγ increases AT inflammation and insulin resistance." (PMID 34248937, 2021). "Contrary to our finding, Kubota and colleagues reported that heterozygous PPARγ-deficient mice were protected from the development of insulin resistance caused by adipocyte hypertrophy after HFD-feeding." (PMID 32973516, 2020). "A family-based study of Mexican Americans showed that variation in PPARG contributes to declining insulin resistance and concomitant deterioration in β-cell function at risk for T2D." (PMID 32143602, 2020). "PPARα was previously shown to mediate fatty acid oxidation in liver, while PPARγ is linked to insulin resistance and lipid storage in adipocytes." (PMID 32728158, 2020). "Accordingly, various point mutations in the Pparγ gene, which result in familial partial lipodystrophy are accompanied by severe insulin resistance." (PMID 33198317, 2020). "Decreased PPARγ levels are associated with development of insulin resistance and failure of lipolysis in obese pregnant women." (PMID 32773037, 2020). "Previous studies have shown that PPARγ hyperglycosylation modification induces endothelial insulin resistance and dysfunction associated with diabetic vascular complications by regulating the eNOS-NO pathway." (PMID 33293942, 2020). "PPARγ expression in the adipose tissue is associated with HD-induced adipocyte hypertrophy and insulin resistance." (PMID 33138026, 2020). "PPARγ agonism is used clinically to reduce insulin resistance and improve hyperglycemia associated with type 2 diabetes, however, this treatment markedly elevates TG levels in the liver associated with a number of murine models of diabetes or obesity." (PMID 30871156, 2019). "RSG, the PPARγ agonist and a member of the thiazolidinediones (TZDs) family has been currently assessed for the diseases associated with insulin resistance." (PMID 31470514, 2019). "According to its functions, PPARγKO mice do not develop adipose tissue and, in humans, a dominant negative mutation in a single allele of PPARG (encoding for PPARGγ) leads to insulin resistance and lipodystrophy phenotype." (PMID 30893897, 2019). "Mutations in the gene coding for PPARγ are clearly related to an obese phenotype and insulin resistance in humans." (PMID 30893897, 2019). "Cdk5-mediated phosphorylation of PPARγ at S273 induced by HFD has been linked to insulin resistance." (PMID 30008738, 2018). "Deletion of PPARγ from adipose tissue caused lipodystrophy and confirmed the prominent role of PPARγ in adipocyte differentiation and metabolism, while PPARγ deletion from skeletal muscle caused insulin resistance." (PMID 30011852, 2018). "Especially, PPARG rs17793951 and rs2920502 are associated with insulin resistance and the higher risk of metabolic syndrome by regulating the expression of adiponectin." (PMID 29495392, 2018). "Consistent with this, patients with mutations of PPARγ develop lipodystrophy and insulin resistance." (PMID 30037087, 2018). "Previous reports also suggest that PPARγ deficiency selectively in the subcutaneous AT during aging is associated with increased AT expansion that is associated with the development of insulin resistance." (PMID 30037087, 2018). "Both isoforms of PPARγ, PPARγ1 and PPARγ2, are necessary for the adipogenic function, and alteration in their expression increases susceptibility to lipodystrophy, insulin resistance, and T2D." (PMID 30037087, 2018). "Macrophage expression of PPARγ is required for their polarization toward an anti-inflammatory phenotype, and mice deficient in PPARγ in their macrophage population are more prone to whole-body insulin resistance." (PMID 29514067, 2018). "In clinic, patients with heterozygous PPARγ mutation show partial lipodystrophy and insulin resistance." (PMID 30186237, 2018).
Insulin resistance (continued). "A role for PPARγ in insulin resistance is evident in that several dominant negative PPARγ mutations are present in some patients with severe insulin resistance." (PMID 29570618, 2018). "Here, we show that ablation of the nuclear receptor PPARγ specifically in inguinal fat tissue in aging mice is associated with increased fat tissue expansion and insulin resistance." (PMID 29383825, 2018). "HFD can activate the expression of C/EBPα and PPARγ in tissues and cause hyperglycemia resulting from diet-induced early insulin resistance through hematogenous spread." (PMID 28358328, 2017). "In support, specific deletion of PPARγ in adipose causes lipodystrophy, global insulin resistance and hyperglycemia in mice." (PMID 28515350, 2017). "Mutations within the DBD of human PPARG inhibit the transcriptional potential of PPARG and patients carrying such mutations exhibit severe insulin resistance and an increased risk for diabetes." (PMID 28588550, 2017). "In this study, we found altered mediators implicated in insulin resistance and cognition, including adiponectin, PPARγ, ERK1/2, p66Shc, SIRT1 and BDNF." (PMID 29340106, 2017). "PPARγ H449L mutation was associated with hypertriglyceridemia, insulin resistance, and NAFLD in four patients related with variable severity in the clinical features." (PMID 27483259, 2016). "The mutations resulting in the loss of function of peroxisome proliferator-activated receptor γ (PPARγ) underlie the development of severe insulin resistance and overt type 2 diabetes." (PMID 27689988, 2016). "Loss of hepatic PPARγ increased TG blood level and redistribution to other tissues, aggravating insulin resistance in muscle and adipose tissue." (PMID 28115925, 2016). "Patients with dominant-negative mutations in a single allele of PPARγ have partial lipodystrophy and insulin resistance." (PMID 27483259, 2016). "Somehow, the metabolic impairment caused by insulin resistance is able to deteriorate both PPARG and VD/VDR system." (PMID 27579030, 2016). "Insulin resistance was developed in Apo E deficient mice fed a high fat diet, and these mice developed PH that was ameliorated with rosiglitazone induced activation of PPARγ." (PMID 27376089, 2016). "On the contrary, gradual reduction of PPARγ as well as PPARγ mutation resulted in insulin resistance, in association with lipodystrophy." (PMID 27176632, 2016). "Heterozygous PPARγ deficient mice display improved insulin resistance and dyslipidemia induced by a high-fat diet, but body weights similar to mice on a normal diet." (PMID 27176632, 2016). "In recent years, research has found that decreasing the activity of PPARγ by constructing PPARγ gene knockout models or inducing mutations at PPARγ activity sites can relieve the insulin resistance induced by a high fat diet." (PMID 25574213, 2015). "A low VO2max has been shown to be associated with glucose intolerance, insulin resistance, type-2 diabetes mellitus, and downregulation of the PPARG mRNA expression from skeletal muscle and peripheral mononuclear cells." (PMID 25879043, 2015). "These factors act in concert to cause adipocyte dysfunction and insulin resistance directly by decreasing insulin signaling, or indirectly by inducing inflammatory gene expression and interfering with PPARγ activity." (PMID 26030149, 2015). "This leads to PPARγ transcriptional activation and downstream effects such as the mild metabolic syndrome and the associated insulin resistance." (PMID 26083030, 2015). "Mutations in PPARγ cause lipodystrophies, and in some severe cases, causes early onset insulin resistance, type 2 diabetes and hypertension." (PMID 25122005, 2014). "On the other hand, the PPARG Pro12Ala, particularly the 12Ala has been associated with a reduced risk of type 2 diabetes and insulin resistance." (PMID 24447396, 2014). "In this study, we show that PPARG Pro12 is significantly associated with insulin resistance and type 2 diabetes in this population." (PMID 24447396, 2014).